NOLC1 (nucleolar and coiled-body phosphoprotein 1)
Description:
Nucleolar protein that acts as a regulator of RNA polymerase I by connecting RNA polymerase I with enzymes responsible for ribosomal processing and modification. Required for neural crest specification: following monoubiquitination by the BCR(KBTBD8) complex, associates with TCOF1 and acts as a platform to connect RNA polymerase I with enzymes responsible for ribosomal processing and modification, leading to remodel the translational program of differentiating cells in favor of neural crest specification. Involved in nucleologenesis, possibly by playing a role in the maintenance of the fundamental structure of the fibrillar center and dense fibrillar component in the nucleolus. It has intrinsic GTPase and ATPase activities.
Synonyms: Nopp140; KIAA0035; NS5ATP13; P130; NOPP130; Srp40
Tractability: PROTAC: UniProt records ubiquitination sites on it; ubiquitination databases record sites on it; its protein half-life has been measured.
Gene: Protein-coding gene on chromosome 10 (102,152,175 to 102,163,875, forward strand). Ensembl gene ENSG00000166197.
Subcellular location: Nucleus, nucleolus; Cytoplasm
Subcellular location (Human Protein Atlas): Nucleoli fibrillar center
Gene Ontology:
Molecular function: molecular function inhibitor activity; protein binding; protein heterodimerization activity; protein kinase inhibitor activity; protein-macromolecule adaptor activity; RNA binding
Biological process: negative regulation of protein serine/threonine kinase activity; neural crest cell development; neural crest formation; regulation of translation; mitotic cell cycle; ribosome biogenesis; rRNA processing
Cellular component: fibrillar center; nucleolus; cytoplasm; nucleoplasm
Genetic constraint (gnomAD): Loss-of-function variants: 37 observed, 76.09 expected, observed/expected ratio (o/e) 0.49, 90% interval 0.37 to 0.64. The upper end of that interval is the gene's LOEUF score, 0.64, which puts it in group 2 of 6, group 1 being the genes least tolerant of losing a copy. Missense variants: 921 observed, 880.27 expected, observed/expected ratio (o/e) 1.05, 90% interval 0.99 to 1.11. Synonymous variants: 327 observed, 318.1 expected, observed/expected ratio (o/e) 1.03, 90% interval 0.94 to 1.13.
Homologues: Orthologues: chimpanzee NOLC1 (99% identical), macaque NOLC1 (94% identical), dog NOLC1 (83% identical), pig NOLC1 (82% identical), rat Nolc1 (75% identical), guinea pig NOLC1 (75% identical), mouse Nolc1 (74% identical), tropical clawed frog nolc1 (43% identical), zebrafish nolc1 (41% identical), Caenorhabditis elegans dao-5 (35% identical).
Diseases named in the same sentence as NOLC1 in open-access papers:
NOLC1 is named in the same sentence as 40 diseases in open-access papers, as found by Europe PMC text mining. Sharing a sentence is not in itself a finding about the gene and the disease. The quoted sentences say what the papers report.
breast carcinoma (11 papers, 2017 to 2025). "PrognoScan and Kaplan-Meier plotter analyses revealed that high expression of NOLC1 was associated with poor prognosis in both all breast cancer and TNBC patients." (PMID 35174077, 2022). "Kaplan-Meier survival curves revealed that high expression of NOLC1 was associated with poor prognosis in both all breast cancer and TNBC patients." (PMID 35174077, 2022). "Since the TNBC phenotypes are similar to stemness properties, we speculate that the high NOLC1 level might be associated with poor outcomes in breast cancer patients." (PMID 35174077, 2022). "Therefore, it is conceivable that high NOLC1 expression is a potential independent risk factor for OS of breast cancer patients." (PMID 35174077, 2022). "Important stemness regulators MYC and ALDH have lower protein levels in breast cancer cells when NOLC1 is knocked down, which prevents the cells from forming spheres." (PMID 39789998, 2025). "We found that NOLC1 expression was higher in breast cancer tissues compared with normal tissues in 5 out of the 6 datasets available." (PMID 35174077, 2022). "We also performed survival analysis in HER2-positive breast cancer patients, which revealed that high expression of NOLC1 predicted better RFS in HER2-positive breast cancer (data not shown)." (PMID 35174077, 2022). "NOLC1 was found to be expressed at a higher level in TNBC than in any other subtype of breast cancer." (PMID 35174077, 2022). "In our study, GSEA showed that the stemness-related pathways were significantly enriched in breast cancer with high NOLC1 expression." (PMID 35174077, 2022). "We further explored the correlation between NOLC1 expression and the stemness-related genes in basal-like breast cancer (BLBC)." (PMID 35174077, 2022). "In order to further investigate the expression of NOLC1 in various subtypes of breast cancer, we used the UALCAN database." (PMID 35174077, 2022). "The impact of NOLC1 expression on the survival of breast cancer patients was evaluated using the PrognoScan database." (PMID 35174077, 2022). "GSEA analysis revealed that stemness-related pathways were significantly enriched in breast cancer with high NOLC1 gene expression." (PMID 35174077, 2022). "In our study, bioinformatics analysis of high throughput RNA-sequencing data from TCGA revealed significantly increased NOLC1 expression in breast cancer tissues compared with the adjacent breast tissues." (PMID 35174077, 2022). "Consistent with the results of univariate analysis, multivariate Cox analysis showed that high NOLC1 expression predicted poor OS of breast cancer patients (HR = 1.35, 95% CI = 1.14–1.6, P < 0.001)." (PMID 35174077, 2022). "For example, NOLC1 produces eight protein isoforms, although only two isoforms are highly expressed in breast cancer cell lines." (PMID 31554914, 2019). "In breast cancer, NOLC1 is substantially enriched in pathways relevant to stem cells." (PMID 39789998, 2025). "NOLC1, PAICS, and TEX10 expression are associated with cancer stemness, poor prognosis, and resistance to interventional chemo/radiotherapy in patients with breast cancer, esophageal cancer, hepatocellular carcinoma or melanoma." (PMID 37435077, 2023). "Moreover, results obtained from protein-protein interaction analysis also showed that ribosome biogenesis-related proteins including NOLC1 interacted with markers of stemness in breast cancer." (PMID 35174077, 2022). "Furthermore, we analyzed the relationship between NOLC1 expression and the prognosis of breast cancer patients by univariate and multivariate Cox regression, PrognoScan, and Kaplan-Meier plotter analyses." (PMID 35174077, 2022). "In the present study, we downloaded the TCGA dataset from the cBioPortal database and comprehensively analyzed NOLC1 expression in both all breast cancer and TNBC patients using web-based databases including Oncomine, tumor immune estimation resource 2.0 (TIMER2.0), and UALCAN." (PMID 35174077, 2022).
breast carcinoma (continued). "In the current study, based on bioinformatics analysis of the online databases, we found that the expression of NOLC1 was higher in breast cancer tissues than normal tissues, and NOLC1 was expressed at a higher level in TNBC than other subtypes of breast cancer." (PMID 35174077, 2022). "Next, we investigated whether NOLC1 expression was correlated with prognosis in breast cancer patients." (PMID 35174077, 2022). "As expected, NOLC1 was expressed at a higher level in TNBC than other subtypes of breast cancer." (PMID 35174077, 2022). "Further analyses using the GEPIA2 and TIMER2.0 databases revealed that NOLC1 was positively correlated with stemness-related genes, including MYC, ALDH18A1, ALDH1A1, SMAD2, SMAD3, etc., in both all breast cancer and TNBC." (PMID 35174077, 2022). "Further immunohistochemical analysis of breast cancer patient samples revealed that TNBC cells had a lower level of NOLC1 in the nucleus compared with non-TNBC cells." (PMID 35174077, 2022). "Transcript levels of five of the seven metabolic genes (TALDO1, GPI, SHMT2, LDHA, and ADK: 5-gene metabolic signature) and six oncogenes: TAGLN2, NOLC1, HSP90AB1, HDGF, MCM5, and NCL, were elevated in TNBC patients when compared to patients with ER+ breast cancer." (PMID 34711841, 2021). "For example, the interaction of Zyxin with NOLC1 (Nucleolar and coiled-body phosphoprotein 1) and BCAR1 (Breast cancer anti-estrogen resistance protein 1) suggest a novel role of zyxin in ribosomal processing and in tyrosine kinase-based signaling, respectively." (PMID 33808029, 2021). "Among the candidates unique to our study are several proteins described to be involved in different cancer types in humans: for example, NOLC1 in multidrug resistant non-small cell lung cancer (the same cancer MALAT1 has originally been identified), DEK in breast cancer and SUB1 in prostate cancer." (PMID 32050583, 2020). "Intriguingly, it was recently reported that lncRNAs (TROLL-2 and TROLL-3) could counteract the interaction between WDR26 and NOLC1, while promoting the combination of WDR26 and AKT to activate the PI3K/AKT pathway in lung cancer cells, human breast carcinoma cells, and human melanoma cell lines." (PMID 34046062, 2021). "However, it’s not known whether NOLC1 expression is higher in TNBC than other breast cancer subtypes and whether it is correlated with the prognosis of TNBC patients." (PMID 35174077, 2022).
nasopharyngeal carcinoma (9 papers, 2013 to 2025). A carcinoma arising from the nasopharyngeal epithelium. "Deregulation of NOLC1 has been observed in various cancer types, which is associated with poor prognosis in patients with nasopharyngeal carcinoma or lung cancer." (PMID 34046062, 2021). "Contrarily, Hwang and colleagues reported that NOLC1 induces tumorigenesis in nasopharyngeal carcinoma." (PMID 40367575, 2025). "A previous study has shown that NOLC1 is expressed at a higher level in nasopharyngeal carcinoma tissues than in normal tissues and is involved in tumorigenesis." (PMID 35174077, 2022). "In nasopharyngeal carcinoma, NOLC1 and tumor protein 53 synergistically co-regulated a cellular proto-oncogene MDM2, leading to cell growth and reduction of apoptosis." (PMID 30505321, 2018). "HELLS is overexpressed in many human tumors and has been shown to hinder cell cycle re-entry and cellular growth whereas NOLC1 expression is crucial for the growth of nasopharyngeal carcinomas." (PMID 24892549, 2014). "But when NOLC1 expression is down-regulated under the interference of shNOLC, the expression of MDM2 proto-oncogene is inhibited while the expression of the apoptosis-related genes (such as TNF-α) were up-regulated in nasopharyngeal carcinoma (NPC) cells." (PMID 34837693, 2021).
prostate carcinoma (7 papers, 2020 to 2025). A carcinoma that arises from epithelial cells of the prostate gland. "For instance, circRNA nucleolar and coiled-body phosphoprotein 1, circRNA formin 1, circ-0016068, circ_0088233 and circ0005276 are all upregulated in prostate cancer and promote the development of prostate cancer." (PMID 34395419, 2021). "In addition, NOLC1 also plays a role in the development of prostate cancer and is highly expressed in cancer tissues." (PMID 35174077, 2022). "According to our research, NOLC1 expression in LUAD was strongly expressed, which is in line with the pattern of expression in colorectal and prostate cancers." (PMID 39789998, 2025). "Eighty-two percent blood samples from the prostate cancer patients were positive for MAN2A1-FER transcript, while 41.5% and 38.8% blood samples from the prostate cancer patients were positive for SLC45A2-AMACR and Pten-NOLC1, respectively." (PMID 34417538, 2021). "The next most frequent fusion transcripts present in the blood samples from the prostate cancer patients were SLC45A2-AMACR and Pten-NOLC1, accounting for 41.5% (61/147) and 38.8% (57/147), respectively." (PMID 34417538, 2021).
esophageal cancer (5 papers, 2021 to 2025). A primary or metastatic malignant neoplasm involving the esophagus. "In this study, we first used The Cancer Genome Atlas (TCGA) data to conduct a pan-cancer analysis on NOLC1 expression and found that NOLC1 expression was elevated in colorectal cancer, esophageal cancer, bile duct cancer, and other tumor tissues." (PMID 37670166, 2023). "The results of the correlation between NOLC1 gene expression and overall survival using Kaplan–Meier plotter for patients with esophageal cancer coincided with the data obtained for patients with gastric cancer, evaluated in our study." (PMID 37765273, 2023). "We further measured the expression of NOLC1 in five esophageal cancer cell lines (EC9706, Eca109, TE-13, Kyse170, T.TN) and normal esophageal cell line HEEC by QRT-PCR and western blot assay." (PMID 34046062, 2021). "In esophageal cancer (ESCA), NOLC1 can activate the PI3K-AKT signaling pathway." (PMID 40864495, 2025).
hepatocellular carcinoma (5 papers, 2013 to 2023). A malignant tumor that arises from hepatocytes. "According to several studies, NOLC1 localized in the nucleolus interacts with telomeric repeat-binding factor 2 (TRF2), and the overexpression of NOLC1 inhibits cell proliferation by inducing apoptosis and cell cycle arrest in hepatocellular carcinoma." (PMID 35174077, 2022). "NOLC1 plays an important role in the regulation of cell growth, inflammation genesis, and hepatoma development." (PMID 23188192, 2013). "Besides, NOLC1 exhibited a low expression in hepatocellular carcinoma tissues and overexpression of NOLC1 inhibited hepatocellular carcinoma cells proliferation." (PMID 33490086, 2020). "Recent results have shown that NOLC1 may play an important role in the regulation of cell growth, inflammation genesis, and hepatoma development." (PMID 23188192, 2013). "Additionally, NOLC1 expression was decreased in human hepatocellular carcinoma (HCC) tissue, and the ectopic expression of NOLC1 repressed the proliferation of HCC cells and tumor growth in a HCC xenograft model." (PMID 28493459, 2017). "In contrast, NOLC1 expression is lower in human hepatocellular carcinoma tissues compared with the matched non-cancerous tissues, and overexpression of NOLC1 suppresses cell proliferation of hepatocellular carcinoma." (PMID 35174077, 2022).
clear cell renal cell carcinoma (4 papers, 2021 to 2025). "However, NOLC1 acts as a tumor suppressor in clear cell renal cell carcinoma." (PMID 40864495, 2025). "Mechanistically, previous studies have shown that ZIC2 is highly expressed in clear cell renal cell carcinoma (ccRCC) and promotes the proliferation and migration of ccRCC by regulating the expression of the downstream target gene Runx2 and the ZIC2/Runx2/NOLC1 signaling axis." (PMID 37479694, 2023).
lung carcinoma (4 papers, 2017 to 2024). "NOLC1 is also a novel nucleolar GTPase/ATPase and is reported to play a role in the regulation of tumorigenesis of lung cancer." (PMID 30505321, 2018).
ovarian carcinoma (4 papers, 2021 to 2025). A malignant neoplasm originating from the surface ovarian epithelium. "In ovarian cancer (OC), circ-NOLC1 binds to ESRP1 and upregulates CDK1 and RhoA expression to promote OC progression." (PMID 40864495, 2025). "The results showed that circ-NOLC1 expression was significantly higher in borderline and ovarian cancers than in normal and benign ovarian tissues (p < 0.05)." (PMID 33483472, 2021). "The results of the present study have showed that circ-NOLC1 expression was significantly higher in ovarian cancer tissues than in normal ovarian tissues." (PMID 33483472, 2021). "We demonstrated that circ-NOLC1 promotes ovarian cancer tumorigenesis and development by binding to ESRP1 and modulating CDK1 and RhoA levels." (PMID 33483472, 2021). "Among ovarian cancer cell lines, circ-NOLC1 expression was the highest in A2780, and lowest in CAOV3." (PMID 33483472, 2021). "Circ-NOLC1 expression in normal ovarian tissues, benign tissues, borderline tumor tissues, and ovarian carcinoma tissues was assessed using quantitative real-time reverse transcription PCR (qRT-PCR)." (PMID 33483472, 2021). "An extensive literature search revealed that ESRP1 was also overexpressed in ovarian cancer tissues; therefore, we suggested that circ-NOLC1 could bind with ESRP1 and modulating CDK1 and RhoA expression." (PMID 33483472, 2021). "In this case, we demonstrated the role of circ-NOLC1 in epithelial ovarian cancer (EOC)." (PMID 33483472, 2021). "Therefore, in the present study, we investigated the role of circ-NOLC1 in ovarian cancer and attempted to determine how circ-NOLC1 affects the development of ovarian cancer through a series of in vivo and in vitro experiments." (PMID 33483472, 2021). "Thus, we hypothesized that circ-NOLC1 could promote ovarian cancer development by binding with miRNAs that inhibit the translation of CDK1 and RhoA." (PMID 33483472, 2021). "Thus, we hypothesized that circ-NOLC1 might participate in ovarian cancer tumorigenesis and progression by binding the ESRP1, thus modulating RhoA and CDK1 expression." (PMID 33483472, 2021). "However, the circular structure of circ-NOLC1, its relationship with NOLC1, and the most important, its role in ovarian cancer tumorigenesis and progression remains unclear." (PMID 33483472, 2021). "Thus, we hypothesized that circ-NOLC1 might participate in ovarian cancer tumorigenesis and progression." (PMID 33483472, 2021). "circ-NOLC1 bound to ESRP1, and circ-NOLC1 overexpression significantly increased the levels of ESRP1 protein and mRNA in ovarian cancer cells." (PMID 38110955, 2023). "Circ-NOLC1 expression in FIGO stage II–IV disease was higher than that in stage I, and in moderate and poor differentiation than in the well differentiation ovarian cancer tissues." (PMID 33483472, 2021).
Treacher-Collins syndrome (4 papers, 2016 to 2024). A congenital disorder of craniofacial development characterized by bilateral symmetrical oto-mandibular dysplasia without abnormalities of the extremities, and associated with several head and neck defects. "In the nucleolus, NOLC1 forms a complex with its paralogue TCOF1, a protein mutated in ribosomopathy manifested as Treacher-Collins Syndrome (TCS)." (PMID 36411431, 2022).
gastric cancer (3 papers, 2023 to 2025). A primary or metastatic malignant neoplasm involving the stomach. "NOLC1 silence rendered gastric cancer (GC) susceptible to ferroptosis." (PMID 40864495, 2025). "In addition, it turns out, in the pan-cancer analysis, NOLC1 was mutated in a variety of cancers, such as endometrial cancer, gastric cancer, skin melanoma, etc., with only 2.19% (13/594) of the genetic changes in colorectal cancer." (PMID 37670166, 2023). "NOLC1 promoted cisplatin (Cis) resistance in gastric cancer (GC)." (PMID 40864495, 2025). "NOLC1 was upregulated in gastric cancer (GC) and a cisplatin (Cis)-resistant GC cell line." (PMID 40864495, 2025). "The selection of target proteins was guided by overexpression data obtained from gastric cancer cell lines, specifically focusing on genes such as AJUBA, CD80 and NOLC1." (PMID 37765273, 2023).
cutaneous melanoma (2 papers, 2023 to 2025). A primary melanoma arising from atypical melanocytes in the skin. "We also compared the NOLC1 expression in human cutaneous melanomas (TCGA data set) with normal skin tissue from the Genotype-Tissue Expression (GTEx) project." (PMID 41227344, 2025).